RNU6-1122P (RNA, U6 small nuclear 1122, pseudogene)
Gene: Small nuclear RNA gene on chromosome 2 (182,873,841 to 182,873,947, forward strand). Ensembl gene ENSG00000207178.
Homologues: Orthologues: chimpanzee U6 (97% identical), pig U6 (94% identical), mouse Gm24584 (93% identical), rabbit U6 (93% identical), rat U6 (92% identical), dog U6 (88% identical), dog U6 (87% identical), pig U6 (87% identical), guinea pig U6 (83% identical). Paralogues in human: RNU6-15P (93% identical), RNU6-25P (93% identical), RNU6-33P (93% identical), RNU6-41P (93% identical), RNU6-574P (93% identical), RNU6-1 (92% identical), RNU6-1011P (92% identical), RNU6-1060P (92% identical), RNU6-12P (92% identical), RNU6-13P (92% identical), RNU6-17P (92% identical), RNU6-18P (92% identical), and 1286 more.